RUNX1 (RUNX family transcription factor 1)
Diseases named in the same sentence as RUNX1 in open-access papers (continued):
Sharing a sentence is not in itself a finding about the gene and the disease.
benign neoplasm (1 paper, 2021). A neoplasm which is characterized by the absence of morphologic features associated with malignancy (severe cytologic atypia, tumor cell necrosis, and high mitotic rate). "Meanwhile, patients with PDAC had a higher expression of RUNX1/SLC2A1/ HK1 axis than patients with benign neoplasms." (PMID 34021267, 2021).
neurodegenerative disease (1 paper, 2024). A disorder of the central nervous system characterized by gradual and progressive loss of neural tissue and neurologic function. "The accumulated evidence of linkage between neurodegenerative diseases and LoY, combined with the role of RUNX1 in pain neuron development, and according to our description of UTY/TLE1-RUNX1 coregulation; such linkage is still not clear to us." (PMID 38817386, 2024).
RUNX1 also shares sentences with these, for which no sentence is quoted: myeloma (6 papers); Thrombocytosis (6); eosinophilia (5); Ewing sarcoma (5); childhood cancer (4); chronic lymphocytic leukemia (4); lung squamous cell carcinoma (4); mastocytosis (4); metabolic disease (4); monocytic leukemia (4); oral squamous cell carcinoma (4); Splenomegaly (4); eczema (3); erythroleukemia (3); immune disorders (3); megakaryoblastic leukemia (3); myeloid sarcoma (3); systemic lupus erythematosus (3); acute erythroid leukemia (2); acute monoblastic leukemia (2); Acute myelomonocytic leukemia (2); acute myocardial infarction (2); adenovirus infection (2); alopecia (2); Arthritis (2); cardiomyopathy (2); chronic eosinophilic leukemia (2); colorectal tumor (2); Crohn disease (2); cutaneous melanoma (2).
A further 146 diseases each share a sentence with RUNX1 in 2 papers or fewer.